RN7SL766P (RNA, 7SL, cytoplasmic 766, pseudogene)
Gene: Miscellaneous RNA gene on chromosome 13 (21,790,537 to 21,790,845, forward strand). Ensembl gene ENSG00000244197.
Homologues: Orthologues: chimpanzee Metazoa_SRP (99% identical), macaque Metazoa_SRP (93% identical). Paralogues in human: RN7SL1 (76% identical), RN7SL3 (76% identical), RN7SL2 (76% identical), RN7SL220P (75% identical), RN7SL126P (75% identical), RN7SL444P (74% identical), RN7SL44P (74% identical), RN7SL797P (74% identical), RN7SL88P (73% identical), RN7SL200P (73% identical), RN7SL296P (73% identical), RN7SL783P (73% identical), and 701 more.